DLGAP2 (DLG associated protein 2)
Diseases named in the same sentence as DLGAP2 in open-access papers:
DLGAP2 is named in the same sentence as 47 diseases in open-access papers, as found by Europe PMC text mining. Sharing a sentence is not in itself a finding about the gene and the disease. The quoted sentences say what the papers report.
autism (25 papers, 2011 to 2025). Persistent deficits in social interaction and communication and interaction as well as a markedly restricted repertoire of activity and interest as well as repetitive patterns of behavior. "Hypermethylated cytosine sites of DLGAP2 gene has been associated with neuropsychiatric disorder including autism and SZ disorder." (PMID 34630024, 2021). "Taken together, these studies suggest that the DLGAP2 gene is likely a common susceptible gene between schizophrenia and autism." (PMID 24416398, 2014). "In that study, we detected several common and rare genetic variants of the DLGAP2 gene associated with autism." (PMID 24416398, 2014). "DLGAP2 is a membrane-associated protein that plays a role in synapse organization and signaling in neuronal cells, and as previously stated, is implicated in the etiology of autism." (PMID 40613785, 2025). "In addition, cannabis use in humans causes in the sperm the hypomethylation at 9 CpG sites located in intron 7 of the autism candidate gene Discs-Large Associated Protein 2 (DLGAP2), a gene involved in synapse organization and neuronal signalling." (PMID 32046164, 2020). "Rare de novo CNVs, deletions, and duplications of DLGAP2 have been reported in individuals with ASD, but how mutations of DLGAP2 contribute to autism is still largely unknown." (PMID 27909399, 2016). "Notably, CLN8 and DLGAP2 are associated with autism, epilepsy and intellectual disabilities." (PMID 40790240, 2025). "There were eight hits on discs large homolog-associated protein 2 (DLGAP2), which is a protein known to be involved in synaptic scaffolding and the previously implicated ion autism development." (PMID 36834053, 2023). "The list of common genes also includes DLGAP2, the gene hypomethylated in the sperm of cannabis users and related to paternal trans-generational inheritance of autism in rodents." (PMID 37174181, 2023). "The Discs-Large Associated Protein 2 (DLGAP2), which is involved in synapse organization and neuronal signaling and has been strongly implicated in autism, was found to be hypomethylated in cannabis users’ sperm as compared with non-users." (PMID 35565034, 2022). "Family-specific deletions at 6q12 and at 8p23.3 containing the DLGAP2 gene, a candidate gene for autism, were ranked high in creativity." (PMID 23460800, 2013). "Discs-large associated protein 2 (DLGAP2) is a synaptic protein previously linked with schizophrenia and autism which has been found to be epigenomically altered in cannabis dependence with changes heritable through the paternal line of rats into the nucleus accumbens of offspring." (PMID 36612763, 2022). "Notably, these included transcripts for adhesion proteins such as CDH13, CDH9, CDH15 and SLITRKs, all strongly linked to ASD, presynaptic molecules such as SYNIII and SV2C, associated with non-syndromic autism and SCZ, and post-synaptic transcripts such as DLGAP2 and GRIN2D, linked to SCZ." (PMID 30185603, 2018). "Some researchers propose that DLGAP2, MCPH1 and NEF3 are the candidate genes for autism." (PMID 40790240, 2025).
schizophrenia (12 papers, 2014 to 2025). A major psychotic disorder characterized by abnormalities in the perception or expression of reality. "These include a HAQER acting as an intronic brain enhancer in the DLGAP2 locus, a gene implicated in autism spectrum disorder and schizophrenia, and a HAQER within the 3’ UTR of BDH1 that has enhancer activity in cardiomyocytes." (PMID 41279559, 2025). "DLGAP2 encodes the SAP90/PSD-95-associated protein 2 (SAPAP2) that is involved in neuronal synaptic function and has been associated with autism spectrum disorder, schizophrenia, and Alzheimer's disease." (PMID 38765731, 2023). "In this study, we identified a specific haplotype CCACCAACT of the DLGAP2 gene associated with schizophrenia with the odds ratio of 2.5." (PMID 24416398, 2014). "Genotype and allele frequencies of molecular variants of the DLGAP2 gene in patients with schizophrenia and controls." (PMID 24416398, 2014). "Notably, HAQER0043 overlaps an intron-exon boundary in DLGAP2, a gene encoding a postsynaptic scaffold protein linked to schizophrenia, autism spectrum disorder, and Alzheimer’s disease." (PMID 41279559, 2025). "Our results indicate that DLGAP2 is a susceptible gene of schizophrenia." (PMID 24416398, 2014). "Together, our data support that the DLGAP2 is a susceptible gene of schizophrenia." (PMID 24416398, 2014). "Furthermore, the DLGAP2 was located on chromosome 8p23, which is a region linked to schizophrenia." (PMID 24416398, 2014). "This study aimed to examine whether the DLGAP2 gene is also associated with schizophrenia." (PMID 24416398, 2014). "This study aimed to investigate whether the DLGAP2 gene is associated with schizophrenia." (PMID 24416398, 2014). "Several studies pointed out an association between DLGAP2 and ASD, obsessive-compulsive disorder (OCD) and schizophrenia." (PMID 33925474, 2021). "DLGAP2 protein has been connected to a diversity of neurological disorders including schizophrenia fragile x mental retardation, post traumatic stress disorder, ASD." (PMID 34238319, 2021). "Specifically, there is heavy literature on involvement of DLGAP1 in schizophrenia and suggesting DLGAP2 as a candidate gene for ASD and PTSD." (PMID 28870203, 2017). "Yet, genetic changes in DLGAP2 and DLGAP3 are considered as susceptibility factors for schizophrenia." (PMID 28870203, 2017). "Nevertheless, further functional studies are needed to address the relation between increased DLGAP2 gene and schizophrenia." (PMID 24416398, 2014). "DLGAP2 and DLGAP3 have only been linked to schizophrenia in genetic screens." (PMID 28870203, 2017). "The distributions of DLGAP2 haplotypes in schizophrenia and controls." (PMID 24416398, 2014). "Further reporter gene assay of these rare variants except c.−69+13C>T showed significantly elevated promoter activity than the wild type, suggesting increased DLGAP2 gene expression may contribute to the pathogenesis of schizophrenia." (PMID 24416398, 2014). "Notably in the present study, we identified several patient-only variants with enhanced promoter activity, suggesting increased DLGAP2 gene expression may contribute to the pathogenesis of schizophrenia." (PMID 24416398, 2014). "Multiple single nucleotide variations (SNVs) have been reported in DLGAP2 and DLGAP3 genes in schizophrenia patient cohorts." (PMID 28870203, 2017). "These included schizophrenia candidate genes (GRIA1, RIMS1, DLGAP2, GRIN2A, and NRXN1) and several interaction partners." (PMID 25484875, 2014). "We resequenced the putative promoter region and all the exons of the DLGAP2 gene in 523 patients with schizophrenia and 596 non-psychotic controls from Taiwan and conducted a case-control association analysis." (PMID 24416398, 2014). "No functional studies have yet been conducted on DLGAP2 and DLGAP3 in relation to schizophrenia." (PMID 28870203, 2017).
autism spectrum disorder (7 papers, 2013 to 2025). A spectrum of developmental disorders that includes autism, and Asperger syndrome. "The study aimed to investigate whether DLGAP2 is genetically associated with autism spectrum disorders (ASD) in general." (PMID 23915500, 2013). "The DLGAP2 variants were found significantly associated with autism spectrum disorders." (PMID 23977060, 2013). "Dlgap2, which encodes one of the main components of scaffold proteins in postsynaptic density (PSD), has been addressed as a candidate gene in autism spectrum disorders." (PMID 25071926, 2014).
Intellectual disability (4 papers, 2014 to 2025). "The DLGAP2 gene is considered by many authors as a gene responsible for the development of progressive intellectual disability, and CLN8 is thought responsible for intellectual disability and seizures." (PMID 35327368, 2022). "Of the five genes differentially methylated with exposure to maternal smoking, DLGAP2 (discs large homolog-associated protein 2) is of particular importance for IDD, since rare variants in DLGAP2 were identified in progressive epilepsy with mental retardation (EPMR [MIM#610003) as well as ASD." (PMID 39972408, 2025). "This segment contains the OMIM genes DLGAP2, CLN8, and ARHGEF10, which are considered candidate genes for developmental delay, intellectual disability and neurobehavioral disorders." (PMID 40790240, 2025).
post-traumatic stress disorder (3 papers, 2017 to 2022). An anxiety disorder precipitated by an experience of intense fear or horror while exposed to a traumatic (especially life-threatening) event. "Animal studies have pinpointed a link between DLGAP2 and post-traumatic stress disorder (PTSD), which is observed as a result of a traumatic experience." (PMID 28870203, 2017).
age (2 papers, 2025). A temporal measurement of the time period elapsed since an identifiable point in the life cycle of an organism. "Our previous work nominated DLGAP2 as a modifier of age‐related cognitive decline and risk for AD." (PMID 41025221, 2025).
alcohol dependence (2 papers, 2021 to 2023). Physical and psychological dependence on alcohol. "The upstream regions of DLGAP2 gene was identified as a differentially methylated regions (DMR) related to alcohol dependence in an epigenome-wide association study using postmortem tissues." (PMID 34417442, 2021). "Furthermore, DLGAP2 DNA methylation can reflect environmental exposures such as cannabis use and alcohol dependence." (PMID 38765731, 2023).
breast carcinoma (2 papers, 2023). "Significant differences in the validation set of samples were found for seven genes; the combination of the four genes GCM2, ITPRIPL1, CACNA1E, DLGAP2 (AUC = 0.99) showed the highest diagnostic value based on logistic regression for all breast cancer samples." (PMID 37628841, 2023).
cognitive decline (2 papers, 2025). "Although we did not measure sleep patterns in this study, there are reports of sleep disruption in the 5XFAD mouse model, which may explain the marked effects on locomotor activity and cognitive decline in our 5XFAD animals that overexpress DLGAP2." (PMID 41025221, 2025).
depression (2 papers, 2021 to 2026). "Our results showed significant causal genetic evidence for injury-associated DNAm changes at cg24526596 (DLGAP2), cg00157656 (ERICH1), cg12317217 (PCDHA2), and cg12661624 (PTPRN2) on depression onset." (PMID 41995537, 2026). "The present study provided genetic evidence supporting the causal role of DNAm in the onset of depression or PTSD after injury and identified DLGAP2, ERICH1, PCDHA2, and PTPRN2 as the candidate genes worthy of further exploratory investigation." (PMID 41995537, 2026).
epilepsy (2 papers, 2024 to 2025). A brain disorder characterized by episodes of abnormally increased neuronal discharge resulting in transient episodes of sensory or motor neurological dysfunction, or psychic dysfunction. "Some of these variants are found in genes relevant to ASD and epilepsy, including RBFOX1, DLGAP2 and TAOK2." (PMID 38283851, 2024).
agoraphobia (1 paper, 2019). An anxiety disorder characterized by an intense, irrational fear of venturing out into open places or situations in which help (or escape) might not be available should excessive anxiety or panic symptoms develop. "Of OCD cases, a male (OCD75-SB-1213) with a paternally inherited 62 kb duplication of DLGAP2 also had separation anxiety disorder, a Tourette disorder with tic, oppositional defiant disorder, and panic disorders and agoraphobia." (PMID 31602316, 2019).
behavioral disorders (1 paper, 2021). "Both DLGAP2 and ARHGEF10 could be potential candidates for behavioral disorders, in accordance with the phenotype of Dlgap2-/- and Arhgef10-/- mice." (PMID 33925474, 2021).
breast disease (1 paper, 2021). "SNP rs2293973, which is located on chromosome 8 and belongs to DLGAP2, was considered a gene variant unrelated to osteoporosis or breast disease." (PMID 33800915, 2021).
CNS cancer (1 paper, 2020). "We compared the expression levels of FAIM2, DLGAP2, ATP1B1 and RALYL using ONCOMINE databases and found that these 4 genes were significantly downregulated in brain and CNS cancer compared with the normal group." (PMID 33323543, 2020).
cognitive deficits (1 paper, 2025). "Based on our previous work, we hypothesized that an increase in DLGAP2 expression in memory‐relevant brain regions would minimize or prevent cognitive deficits associated with AD neuropathology." (PMID 41025221, 2025). "To determine whether DLGAP2 overexpression could ameliorate AD‐related cognitive deficits, we employed a novel longitudinal CFC paradigm at both 6 and 14 months of age." (PMID 41025221, 2025). "Although we observed that 6‐month 5XFAD animals overexpressing DLGAP2 had diminished LTP compared to GFP‐injected controls, this effect was not present by 14 months and did not coincide with observed cognitive deficits." (PMID 41025221, 2025).
colorectal cancer (1 paper, 2021). A primary or metastatic malignant neoplasm that affects the colon or rectum. "DSVs in SGSM2 and LHFPL3 were relevant to colorectal cancer, whereas ADAP1, DLGAP2, ERC1, and PPP6R2 were related to gynecologic cancer." (PMID 33431054, 2021).
diabetes (1 paper, 2023). "In a nested case–control study of 87 T1D cases and 87 controls from the Diabetes Autoimmunity Study in the Young, we conducted causal mediation analyses at 12 DLGAP2 region CpGs to decompose the effect of family history on T1D risk into indirect and direct effects." (PMID 38765731, 2023). "While DLGAP2 is not a traditional diabetes susceptibility locus, growing evidence suggests its expression may play a role in diabetogenesis." (PMID 38765731, 2023).
glioblastoma (1 paper, 2020). The most malignant astrocytic tumor (WHO grade IV). "We analyzed the FAIM2, DLGAP2, ATP1B1 and RALYL alterations using the cBioPortal online tool for Glioblastoma Multiforme (TCGA, Firehose Legacy)." (PMID 33323543, 2020).
inflammatory bowel disease (1 paper, 2022). A spectrum of small and large bowel inflammatory diseases of unknown etiology. "In addition, 4 of the signals detected when CRC was compared with inflammatory bowel disease patients were suggestive: in the HLA region, in the DLGAP2 gene, downstream of the PTCHD3 gene and upstream of the ATP8B4 gene." (PMID 36077729, 2022).
microcephaly (1 paper, 2021). A congenital or acquired developmental disorder in which the circumference of the head is smaller than normal for the person's age and sex. "Moreover, DLGAP2 interacts with NRXN1, a pre-synaptic cell-adhesion molecule and CASK, another scaffolding protein and mutations in both NRXN1 and CASK are associated to neurodevelopmental and neurocognitive disabilities and microcephaly." (PMID 33925474, 2021). "The CR comprises several genes out of which the OMIM genes FBXO25, DLGAP2, CLN8, ARHGEF10 and MYOM2, most of which share a role in neural differentiation and function, are main candidates for DD/ID, microcephaly and neurobehavioral disorders." (PMID 33925474, 2021). "Weakening of the DLGAP2-NRXN1 interaction upon DLGAP2 haploinsufficiency and interfering with the NRXN1-CASK interaction might concur to microcephaly onset also in 8p23.2-pter patients." (PMID 33925474, 2021).
osteoarthritis (1 paper, 2023). A noninflammatory degenerative joint disease occurring chiefly in older persons, characterized by degeneration of the articular cartilage, hypertrophy of bone at the margins and changes in the synovial membrane. "While Dlgap2 has been implicated as being differentially methylated in both aging and osteoarthritis in mice, no further link with ADA or RA can be identified in the literature." (PMID 38187379, 2023).
neurological disorders (4 papers, 2020 to 2022). "DLGAP2 (SNP: rs72507619, CorrectedP: 3.74049E-17) was found to be predominantly expressed in the brain and associated with a wide variety of neurological disorders." (PMID 35418845, 2022). "The genes that contained most VNTRs, of which PTPRN2 and DLGAP2 are the most prominent examples, were found to be predominantly expressed in the brain and associated with a wide variety of neurological disorders." (PMID 33139705, 2020). "DLGAP2 is primarily studied in neuronal cells and neurological disorders; it may be related to glutamate signaling." (PMID 32111940, 2020).
cancer (3 papers, 2022 to 2023). A tumor composed of atypical neoplastic, often pleomorphic cells that invade other tissues. "In our study, we used a set of 96 tumor samples of less than 2 cm; in this set, the assessment of the methylation of the GCM2, ITPRIPL1, CACNA1E, and DLGAP2 genes most accurately distinguished cancer from healthy tissues." (PMID 37628841, 2023). "The role of DLGAP2 and CCDC144A in malignant tumors is still unclear, but previous studies have suggested that TFAP2A can promote or inhibit cancer progression in tumors." (PMID 38125697, 2023).
neurodevelopmental disorder (3 papers, 2021 to 2024). A behavioral and cognitive disorder with onset during the developmental period that involves impaired or aberrant development of intellectual, motor, or social functions. "In the first case (family 1), the DLGAP2 gene was ranked as the top candidate for a proband with a neurodevelopmental disorder." (PMID 38178268, 2024). "Out of the 11 protein coding genes encompassing the deletion intervals of our patients, DLGAP2 and ARHGEF10 appear to be, according to their expression profile and the assessed role in neural morphogenesis, differentiation and function, bona fide candidates for neurodevelopmental disorders." (PMID 33925474, 2021).
DLGAP2 also shares sentences with these, for which no sentence is quoted: Alzheimer disease (1 paper); Anorexia (1); attention deficit-hyperactivity disorder (1); bipolar disorder (1); cannabis dependence (1); cocaine addiction (1); developmental delay (1); Fibroadenoma (1); fragile X syndrome (1); gout (1); gynecologic cancer (1); Infertility (1); Klinefelter syndrome (1); obsessive-compulsive disorder (1); Oppositional defiant disorder (1); osteoporosis (1); panic disorder (1); psychiatric disorder (1); separation anxiety disorder (1); Tourette disorder (1); tumor (1); type 1 diabetes (1).